SCGB3A1 (secretoglobin family 3A member 1)
Diseases named in the same sentence as SCGB3A1 in open-access papers (continued):
Sharing a sentence is not in itself a finding about the gene and the disease.
cancer (22 papers, 2007 to 2025). A tumor composed of atypical neoplastic, often pleomorphic cells that invade other tissues. "High frequency of methylation of these CpGs is associated with loss of SCGB3A1 expression in many human cancers." (PMID 18194566, 2008). "For the ALT high and TELlow phenotype, the BRIP1 and CLSPN genes were upregulated in 12 different cancer types and the MTND1P23 pseudogene was downregulated in 14 cancer types, and SCGB3A1 in 12 cancer types." (PMID 38763334, 2024). "The study found that phosphorylation of Akt in cancer can effectively inhibit the expression of Scgb3a1." (PMID 31248178, 2019). "APC and SCGB3A1 disclosed 100% specificity for cancer detection, whereas PSAT1 showed the highest sensitivity (91.97%)." (PMID 30405052, 2018). "Among the cancer-specific hypermethylated genes, SCGB3A1 and PPL were already reported to have hypermethylation at its promoter, leading to reduced expression in ESCC." (PMID 29137437, 2017). "Expression of SCGB3A1 is induced during epithelial differentiation and restricted to terminally differentiated airway epithelial cells and down-regulated in cancer." (PMID 22375630, 2012). "Hypermethylated CRABP1, MLH1, NR3C1, RUNX3, and SCGB3A1 were shown to be identifiers of carcinomas with microsatellite instability." (PMID 19117505, 2008). "The methylation frequencies of HOXA9 and SCGB3A1 were higher among relatively early-stage carcinomas (FIGO I-II) than among carcinomas of later stages (FIGO III-IV; P = 0.002, P = 0.020, respectively)." (PMID 17623056, 2007). "Higher expression of SCGB3A1 in GGN-ADC derived fibroblasts may play an important role in cancer cells, which needed to be validated by experiments." (PMID 33083004, 2020). "From the seven most promising candidates, six (APC, CCND2, FOXA1, PSAT1, RASSF1A and SCGB3A1) confirmed its cancer-specificity, discriminating normal from cancerous tissues, although with variable performance, paralleling previous observations from our team and others." (PMID 30405052, 2018). "Since APC, FOXA1 and RASSF1A were biomarkers common to BrC, CRC and LC, they were further tested as gene panel for cancer detection (designated “PanCancer”), whereas RARβ2, SCGB3A1, SEPT9 and SOX17 were considered a gene panel for discrimination of primary cancer localization (“CancerType” panel)." (PMID 30261643, 2018). "For this reason, we hypothesised that SCGB3A1 could be an important biomarker for cancer in non cancerous prostatic tissue." (PMID 27576364, 2016). "In cancer tissue, SCGB3A1 was only weakly correlated to age, whereas the other genes were not." (PMID 27028854, 2016). "Finally, methylation of CRABP1, MLH1, NR3C1, RUNX3, and SCGB3A1 were identifiers of MSI carcinomas." (PMID 19117505, 2008). "OC-X treatments also caused surge upregulation of several important biomarkers within each cancer progression stage, including UCP1, NOSTRIN, SCGB3A1, ENG, EPAS1, SFTPD, and BMP4." (PMID 34069906, 2021). "As for CRC, the significantly higher APC, FOXA1, RARβ2, RASSF1A, SCGB3A1, SEPT9 and SOX17 methylation levels in cancer patients are in line with previous publications, although divergent results have been reported for MGMT." (PMID 30261643, 2018). "Overall, gene methylation frequencies were higher among MSI than among MSS carcinomas, and were statistically significant for CRABP1, MLH1, NR3C1, RUNX3, and SCGB3A1 (P ≤ 0.0001, P ≤ 0.0001, P = 0.001, P ≤ 0.0001, and P = 0.03, respectively)." (PMID 19117505, 2008). "Our data support the view that promoter hypermethylation is a common mechanism involved in ovarian carcinogenesis and four target genes, HOXA9, HOXB5, SCGB3A1, and CRABP1, novel to this cancer type are identified." (PMID 17623056, 2007). "Furthermore, we previously demonstrated that SCGB3A2 (also called UGRP1 (uteroglobin-related protein 1)), another member belonging to the same SCGB3A gene subfamily as SCGB3A1, is a ligand for Syndecan-1 (SDC1) in cancer cells." (PMID 41469838, 2025).
cancer (continued). "This suggested that, as individual genes, INHBB, LAMA1, SCGB3A1 and OPG can indeed promote metastatic colonization, and that coexpression of the four genes may provide a further advantage to cancer cells." (PMID 35469015, 2022).
infection (2 papers, 2022 to 2024). The state of being infected such as from the introduction of a foreign agent such as serum, vaccine, antigenic substance or organism. "In both N40D10/E9 and ML23 Bb, which was pre-incubated and co-injected with SCGB3A1, showed successful infection in mice." (PMID 38503741, 2024).
SCGB3A1 also shares sentences with these, for which no sentence is quoted: adenoid hypertrophy (3 papers); breast invasive carcinoma (2); breast tumor (2); adenocarcinoma (1); allergies (1); inflammation (1); invasive lobular carcinomas (1); lung adenocarcinoma (1); Nasal polyposis (1); Obesity (1); pancreatic ductal adenocarcinoma (1); renal cell carcinoma (1); Sleep apnea (1); soft tissue sarcoma (1); testicular cancer (1).